ENSG00000267698 (novel transcript, antisense to CLIP3 and THAP8)
Synonyms: LOC101927572
Gene: Long non-coding RNA gene on chromosome 19 (36,014,493 to 36,051,117, forward strand). Ensembl gene ENSG00000267698.
Diseases named in the same sentence as ENSG00000267698 in open-access papers:
ENSG00000267698 is named in the same sentence as 1 disease in open-access papers, as found by Europe PMC text mining. Sharing a sentence is not in itself a finding about the gene and the disease.
ENSG00000267698 shares sentences with these, for which no sentence is quoted: ovarian carcinoma (1 paper).